CSMD1 (CUB and Sushi multiple domains 1)
Diseases named in the same sentence as CSMD1 in open-access papers (continued):
Sharing a sentence is not in itself a finding about the gene and the disease.
schizophrenia (continued). "Using Csmd1 KO mice, we assessed several behavioral modalities that are disrupted in schizophrenia: sensorimotor gaiting (as measured using PPI), social interaction, anhedonia (sucrose preference), and sensitivity to a dopaminergic challenge (d-amphetamine induced locomotor response)." (PMID 23284669, 2012). "Hence, both immune and synaptic regulation may mediate the effects of Csmd1 in the development of both schizophrenia and depression-related phenotypes." (PMID 25762938, 2015). "We note ways in which these data enhance our confidence that CSMD1 variation and thus the neuronal properties and connections that CSMD1 modulates play roles in addiction phenotypes and in cognition-related phenotypes that are of likely relevance for schizophrenia." (PMID 26171607, 2015). "Expression of CUB and Sushi multiple domains 1 (CSMD1) is correlated with the development and treatment of schizophrenia." (PMID 35559016, 2022). "Molecular mechanisms which mediate the influence of CSMD1 and MMP16 on brain development and the pathobiology of schizophrenia remain unresolved." (PMID 29163023, 2017). "Moreover, four other schizophrenia associated genes (TCF4, CACNA1C, CSMD1, and C10orf26) identified in that study contain predicted miR-137 binding sites, suggesting that the interplay between miR-137 and its target genes could be involved in the etiology of schizophrenia." (PMID 25250332, 2014). "In this review, we summarise CSMD1 functions in the cellular processes involved in the complement system, metastasis, and Epithelial mesenchymal transition (EMT) and also in the diseases schizophrenia, Parkinson’s disease, and cancer." (PMID 36553598, 2022). "In schizophrenia, the influence of complement is becoming more clear, with an apparent central, but nut fully understood, role for the locally expressed complement inhibitor CUB and Sushi Multiple Domains 1 (CSMD1)." (PMID 34698894, 2021). "For other regulators of the complement pathway, such as CUB and Sushi Multiple Domains 1 (CSMD1), an inhibitor of the complement cascade, some studies show they contribute to behavior changes relevant to schizophrenia, whereas others do not." (PMID 29706957, 2018). "Unfortunately, in our sample sizes, there was no allelic association with schizophrenia for any of the five SNPs [rs7914558 (CNNM2), rs10503253 (CSMD1), rs7004633 (MMP16), rs11191580 (NT5C2) and rs12966547 (CCDC68)] (p > 0.22)." (PMID 24160291, 2013). "Our results suggest that Csmd1 is not essential for a range of behaviors thought to model key aspects of schizophrenia in mice." (PMID 23284669, 2012). "The lack of a significant effect on classical schizophrenia endophenotypes may be due to mouse–human differences in CSMD1." (PMID 25762938, 2015). "Thus, our results suggest that there are no changes in schizophrenia-relevant behaviors in mice lacking transcripts of Csmd1 that include the first exon." (PMID 23284669, 2012).
breast carcinoma (30 papers, 2011 to 2024). "The low expression of CSMD1 was also associated with reduced survival in the breast cancer METABRIC study." (PMID 36553598, 2022). "As a potential tumor suppressor gene, the loss of CSMD1 impaired the morphology of mammary duct and enhanced cell proliferation, migration and invasion in breast cancer." (PMID 34384362, 2021). "The link between reduced CSMD1 expression and a more invasive ductal phenotype is also supported by human breast cancer studies, in which reduced CSMD1 expression was associated with reduced differentiation and increased tumour grade." (PMID 33530646, 2021). "The gene CSMD1, frequently altered in chromoanagenesis, is a known breast cancer tumor suppressor, associated with high tumor grade and poor survival." (PMID 34439350, 2021). "To date, we and others have presented evidence that CSMD1 acts as a tumor suppressor in breast cancer, but molecular mechanisms underlying this function of the protein have not been elucidated." (PMID 34404439, 2021). "An additional SNP in CSMD1 was also found to be associated with breast cancer–free interval (BCFI) in MA." (PMID 32701512, 2020). "The CUB and Sushi multiple domains 1 (CSMD1) is a tumor suppressor gene reported to be associated with poor prognosis in many cancer types including breast cancer, gastric cancer, head and neck squamous cell carcinoma (HNSCC), and hepatocellular carcinoma." (PMID 32617189, 2020). "Loss of CSMD1 expression is associated with poor survival, and it is frequently deleted in breast cancer." (PMID 30545040, 2018). "The analysis of gene mutation data derived from colon and breast cancers showed CSMD1 to be the most frequently mutated gene located on the p arm of chromosome 8." (PMID 30545040, 2018). "Collectively, our results confirm that low levels of CSMD1 in breast cancer cells are associated with more aggressive cancer cell behavior, hence demonstrating the role of CSMD1 as tumor suppressor gene." (PMID 27764775, 2016). "CSMD1 is a large transmembrane protein suggested to act as tumor suppressor on the basis of genetic findings, i.e. mutations and deletions in the CSMD1 gene are associated with different types of cancer including breast cancer." (PMID 27764775, 2016). "The decreased expression of CSMD1 was linked to a shorter overall survival of breast cancer patients." (PMID 27764775, 2016). "Locus rs3824271 found associated with ER status is located in the CSMD1 gene on chromosome 8p23.2, a region reported to be deleted in up to 50% of breast cancers." (PMID 22188678, 2011). "We hypothesized that CSMD1, previously associated with sensitivity to chemotherapy in breast cancer, could also function as a predictive marker for glioma chemotherapy." (PMID 38561856, 2024). "Furthermore, functional assays on the MCF10A breast cancer line found loss of CSMD1 expression enhanced migration and invasion while reducing adhesion to Matrigel and fibronectin." (PMID 36553598, 2022). "CSMD1, a regulator of complement activation and inflammation, has been proposed as a tumor suppressor gene in advanced oral, gastric, prostate and breast cancer and subsequent loss of CSMD1 functionality is associated to poor prognosis and enhanced proliferation, migration and invasion." (PMID 34326338, 2021). "For several years, CSMD1 has been proposed to act as a tumor suppressor since allelic loss, mutations, and methylations in its genomic region have been reported in several malignancies, including breast cancer." (PMID 34404439, 2021). "Furthermore CSMD1 deletion has also been linked to poor prognosis in patients with late stage breast cancer." (PMID 33530646, 2021). "The loss of CSMD1 ﻿has been found to be associated with enhanced cell proliferation, migration and poor prognosis in head and neck squamous cell carcinoma (HNSCCs), lung squamous cell carcinoma (SCCs), melanoma, and breast cancer, suggesting its role as a tumor suppresser." (PMID 34384362, 2021).
breast carcinoma (continued). "CSMD1 has been proven to be a tumor suppressor gene in multiple tumors and has copy number variations, somatic mutations, deletions, aberrant splicing, and chromosome aberrations in leukemia, primary lung cancer, head and neck squamous cell carcinoma, breast cancer, liver cancer, and other cancers." (PMID 34828321, 2021). "Futhermore, CSMD1, as tumor suppressor gene, has been associated with head and neck squamous cell carcinoma and with the tumorigenesis of several other epithelial cancers, including breast cancer with rare variants (deletions) predisposing individuals to breast cancer." (PMID 27716277, 2016). "Among these six genes, five were hypermethylated (GABRA5, ZIC5, GRAMD4, RSPH3, and VCAN), and one was hypomethylated (CSMD1) in breast cancer samples of cases compared to controls." (PMID 36627894, 2022). "In contrast, increasing studies have indicated that the CSMD1 gene is involved in the progression of colorectal cancer, breast cancer and other tumors." (PMID 35412956, 2022). "This study also demonstrated that the overexpression of CSMD1 in breast cancer cell lines BT20 and MCF7 inhibited migration, adhesion, and invasion." (PMID 36553598, 2022). "CSMD1, previously identified as a tumor suppressor gene in various cancer types, including head and neck, lung and breast cancers, has been identified with deletion in 50% of our PDX models, suggesting an important role in aggressive breast cancers." (PMID 36153537, 2022). "A recent deep whole-genome sequencing study identified CSMD1 deletions in 50% of breast cancer patient-derived xenografts, suggesting a role in driving aggressive breast cancer." (PMID 36553598, 2022). "Our results indicate that CSMD1 cross-talks with the EGFR endosomal trafficking cascade in a way that renders highly invasive breast cancer cells sensitive to chemotherapy." (PMID 34404439, 2021). "Human CUB and Sushi multiple domains 1 (CSMD1) is a large membrane-bound tumor suppressor in breast cancer." (PMID 34404439, 2021). "The mRNA expression pattern and clinical relevance of CSMD1 were evaluated in 3520 breast cancers from a modern population-based cohort." (PMID 34404439, 2021). "In our previous study, we showed that CSMD1 expression in breast cancer cells (BCCs) decreased their metastatic potential." (PMID 34404439, 2021). "In our previous study, we showed that CSMD1 mammary gene expression is dramatically decreased in breast cancer patients compared to normal mammary tissue." (PMID 34404439, 2021). "Conversely, knockdown of CSMD1 expression has been shown to increase the deposition of C3b on breast cancer cells." (PMID 33506581, 2021). "CSMD1 coprecipitated SMAD3 in breast cancer cells and human adipocytes, and a reciprocal immunoprecipitation further confirmed the interaction." (PMID 32701512, 2020). "Overexpression of CSMD1 increased CYP19A1 expression levels in breast cancer cells and human adipocytes." (PMID 32701512, 2020). "To assess the role of CSMD1 in AI response in breast cancer cells, we used the MCF7/AC1 cell line because of its high expression of the AI target CYP19A1." (PMID 32701512, 2020). "After a second surgery, mutation analysis of her bilateral breast cancer was performed in a clinical study, which revealed that her metachronous bilateral breast tumors had the same GATA3 and CSMD1 mutations." (PMID 32833091, 2020). "It was noticeable that CSMD1 was reported to be an important oncosuppressor in many tumors including melanoma, breast cancer, head and neck cancer, and colorectal adenocarcinomas." (PMID 30755830, 2019). "Among the genes commonly amplified or deleted in human breast cancer, only amplifications in Myc and Mdm2 and deletions of Cdkna, Cdkn4b, Csmd1 and Ptprd were seen in the mouse tumor panel." (PMID 28430642, 2017).
breast carcinoma (continued). "Following quantification of the densities of individual dots corresponding to a panel of phosphorylated kinases, we observed an overall diminished signaling potential in the MDA-MB-231 breast cancer cells expressing CSMD1 in comparison with CTRL cells." (PMID 27764775, 2016). "Taken together, these data indicate that CSMD1 expression in human breast carcinoma cells attenuates their migratory and invasive traits, both of which are hallmarks of tumor cell aggressiveness." (PMID 27764775, 2016). "We also revealed that expression of CSMD1 in human breast cancer cells BT-20 and MDA-MB-231 significantly inhibited their malignant phenotypes, including migration, adhesion and invasion." (PMID 27764775, 2016). "Here, we assessed the role of CSMD1 as a tumor suppressor gene in the development of breast cancer in vitro and in vivo." (PMID 27764775, 2016). "We revealed that expression of CSMD1 significantly reduced cell motility and migration, adhesion and invasion, as well as the tumorigenic and signaling potential of human breast cancer cells." (PMID 27764775, 2016). "Breast cancer tissues (n = 127) had significantly lower levels of the CSMD1 transcript than normal tissues (n = 32) (p < 0.05)." (PMID 27764775, 2016). "The panel of breast cancer cells used has served as a suitable model to demonstrate that CSMD1 acts as a tumor suppressor." (PMID 27764775, 2016). "This current report is the first to study the effect of CSMD1 expression on the biological properties of epithelial breast cancer cells." (PMID 27764775, 2016). "Observations from the patient tissues and the in vitro data obtained with three different cell lines were confirmed by in vivo experiments with CSMD1 expressing breast cancer cells." (PMID 27764775, 2016). "In summary, we provide experimental evidence for the role of CSMD1 as a tumor suppressor in vitro and in vivo in the progression of breast cancer." (PMID 27764775, 2016). "Taken together, these findings demonstrate the role of CSMD1 as a tumor suppressor gene in breast cancer." (PMID 27764775, 2016). "In fact, CSMD1 expression is frequently lost in breast cancer, whereas CSMD1 loses allelic balance in head and neck squamous cell carcinomas (HNSCC) and lung cancers." (PMID 23505554, 2013). "CSMD1 is considered to be a tumor suppressor gene in many types of cancer, such as breast cancer, colorectal cancer, gastric cancer and HCC; thus, the mutation of the CSMD1 may cause the proliferation of the cancer." (PMID 36761763, 2023). "Additionally, the tumor-inhibiting role of CSMD1 has been established in various cancers, including breast cancer, colorectal cancer, and hepatocellular carcinoma." (PMID 35412956, 2022). "In a xenograft model of human breast cancer, mice injected with MDA-MB-231 breast cancer cells, either alone or with artificially increased CSMD1 expression, found that there was a significant reduction in lung metastasis in the CSMD1-expressing group when compared to the controls." (PMID 36553598, 2022). "Interrogation of the Cancer Genome Atlas (TCGA) has identified alterations in CSMD1 in many malignant tumours such as breast cancer (~5%), prostate cancer (5.7%), bladder urothelial carcinoma (8%), lung cancer (7%), ovarian cancer (7%), liver cancer (7%), and colorectal adenocarcinoma (7.4%)." (PMID 36553598, 2022). "We hypothesized that CSMD1-bearing tumors are sensitive to common breast cancer chemotherapy agents and that CSMD1 expression could therefore be used as a predictive marker of response to therapy." (PMID 34404439, 2021). "A germline variation within the CSMD1 gene predicts aromatase inhibitor response in breast cancer." (PMID 32701512, 2020). "The loss of CSMD1 has been detected in many cases of HNSCC, lung cancer and breast cancer." (PMID 30545040, 2018).
breast carcinoma (continued). "The tumor suppressor role of CSMD1 was strongly supported by our clinical observation that breast cancer tissues had low levels of CSMD1 compared with normal mammary tissues, and the fact that low levels of the transcript were significantly associated with a shorter survival of the patients." (PMID 27764775, 2016). "In the present study, by using in vitro and in vivo approaches, we aimed to determine whether CSMD1 acts as a tumor suppressor protein in breast cancer progression." (PMID 27764775, 2016). "The CSMD1 mRNA expression was examined in three breast cancer cell lines by RT-PCR." (PMID 27764775, 2016). "Next, we measured the expression of CSMD1 transcript in a cohort of human breast cancer using qPCR." (PMID 27764775, 2016). "Focal copy number loss of the CSMD1 gene has been observed in CRC, breast cancer and gastric cancer, and decreased level of CSMD1 expression was reported to be significantly associated with high-tumor grade and reduced overall survival in a breast cancer study." (PMID 24694993, 2014). "Our findings suggest that the CSMD1 SNP might help to predict AI response, and anastrozole plus E2 serves as a potential new therapeutic strategy for patients with AI- or fulvestrant-resistant breast cancers." (PMID 32701512, 2020). "Additionally, analysis of mRNA expression array data for 1600 breast cancer patients with the online survival analysis tool KM plot (kmplot.com) supported the tumor suppressor function of CSMD1 in an independent patient cohort using recurrence-free survival as an endpoint." (PMID 27764775, 2016). "In our previous study, we found that CSMD1 expression is lower in HCC, which is consistent with the results in breast cancer and melanoma." (PMID 27756250, 2016). "Likewise, in chromosome 8, arm-level gains of 8q and losses of 8p in human breast cancer SCNAs were further segmented into three amplification peaks involving STK3, MYC, and PTK2 and three deletion peaks involving CSMD1, PSD3, and IDO1 in hg19-aligned CMT SCNAs, respectively." (PMID 32680987, 2020). "Further, mRNA expression databases for breast cancer patients available online, also did not indicate correlation between mRNA levels of EGFR and CSMD1." (PMID 34404439, 2021).
bipolar disorder (13 papers, 2013 to 2024). A disorder of the brain that causes unusual shifts in mood, energy, activity levels and the ability to carry out day-to-day tasks. "KLC2, PPP3CB, and CSMD1 were associated with mood disorders such as major depressive disorder or bipolar disorder." (PMID 35559016, 2022). "CSMD1 has also been reported to be associated with bipolar disorder and cannabis dependence." (PMID 33384710, 2020).